PDK2 (pyruvate dehydrogenase kinase 2)
Diseases named in the same sentence as PDK2 in open-access papers (continued):
Sharing a sentence is not in itself a finding about the gene and the disease.
cancer (continued). "mRNA expression of PDHα1 (enzymes that convert pyruvate into acetyl-CoA), PDK2/3/4 (inhibitors of PDH), and aconitase (an enzyme of the TCA cycle) was significantly downregulated in the cancer tissue." (PMID 33681091, 2021). "We determined that DCA reduced the abundance of PDK1 in breast (MDA-MB-231) and prostate (PC-3) cancer cells, while it suppressed both PDK1 and PDK2 in skeletal muscle cells (L6 myotubes)." (PMID 34445316, 2021). "Particularly, PDK2 is the most sensitive to dichloroacetic acid, which activates pyruvate dehydrogenase by inhibiting PDK and shifts the metabolism of cancer cells from glycolysis to oxidative phosphorylation." (PMID 27767175, 2016). "Next, we investigated the effect of PDK2 on cancer cell growth through phosphorylation of FOXK2 at Ser9, Thr13 or Ser30 and found that FOXK2 or Ser9-mediated induction of cancer cell proliferation could be induced by PDK2 overexpression in cells." (PMID 38734828, 2024). "Circ-RHOT1 may act as a target for miR-326 to indirectly control PDK2 expression and therefore affect cancer development, whereas circ-RHOT1 positively controlled PDK2 expression by sponging miR-32627." (PMID 37587156, 2023). "In addition, based on the known functional roles in cancer and the reported classification of the kinase family, PRKD1, PRKD3, BCKDK, PDK2, and CSNK2A2 were considered as potential CCA-relative PKs, which were related to the six overlapped PKs." (PMID 36231050, 2022). "In the present study, we demonstrated that the miR-422a–PDK2 axis regulates GC cell lipogenesis and ROS levels, resulting in G1 phase arrest, rather than apoptosis of cancer cells." (PMID 29725130, 2018). "Suppression of PDK2 increases apoptosis of cancer cells via activated OXPHOS, suggesting that it might be used as a therapeutic strategy for treatment of malignant tumors." (PMID 28881758, 2017). "However, the role of PDK2 in paclitaxel resistance of cancer cells has not been studied." (PMID 28881758, 2017). "While Sox2 might not be directly involved in the survival of differentiated cancer cells, its downstream targets like HK2 and PDK2 might be contributing in viability of the cells through their key roles in metabolic processes." (PMID 32170113, 2020).
metabolic disease (6 papers, 2019 to 2025). A congenital disorder (due to inherited enzyme abnormality) or acquired (due to failure of a metabolically important organ) disorder resulting from an abnormal metabolic process. "In contrast, among the four PDK isozymes, PDK2 and PDK4 are the most strongly associated with metabolic diseases, especially type 2-diabetes." (PMID 31134063, 2019). "The role of PDK4 in muscle tissues of well-fed animals without metabolic disorders is secondary, and the major isozyme in these tissues is PDK2." (PMID 40943218, 2025).
infection (4 papers, 2017 to 2025). The state of being infected such as from the introduction of a foreign agent such as serum, vaccine, antigenic substance or organism. "Additionally, RNAi screening highlighted the importance of pyruvate dehydrogenase kinase 2 (PDK2) during infection." (PMID 37374883, 2023).
neurological diseases (1 paper, 2023). "In particular, Pdk2 has been implicated in neurological diseases and plays a crucial role in macrophage polarization to the M1 phenotype." (PMID 36878638, 2023).
PDK2 also shares sentences with these, for which no sentence is quoted: adenocarcinoma (2 papers); head and neck cancer (2); Cerebral ischemia (1); Cognitive impairment (1); fibrosis (1); Glucose intolerance (1); Graves’ orbitopathy (1); hyperuricemia (1); infarction (1); leukemia (1); non-alcoholic fatty liver disease (1); osteoarthritis (1); pulmonary hypertension (1); Seizure (1); squamous cell carcinoma (1); ulcerative colitis (1).